IFI16 (interferon gamma inducible protein 16)
Diseases named in the same sentence as IFI16 in open-access papers (continued):
Sharing a sentence is not in itself a finding about the gene and the disease.
breast cancer (16 papers, 2014 to 2025). A primary or metastatic malignant neoplasm involving the breast. "Supporting an association between IFI16 and tumorigenesis, IFI16 levels are frequently decreased in breast cancer cell lines." (PMID 33981307, 2021). "In addition, high serum IFI16 levels are associated with poor overall survival in breast cancer." (PMID 37998338, 2023). "The reactivation of IFI16-directed immune responses has the potential to convert HER2-positive breast cancer into immunologically active ‘hot tumors’, thereby augmenting patient responsiveness to trastuzumab treatment." (PMID 40386782, 2025). "In the context of HER2-positive breast cancer, CXCL10 emerges as being particularly significant, implicated in trastuzumab responses through interferon-gamma-inducible protein 16 (IFI16)-dependent STING signaling." (PMID 39682150, 2024). "In contrast, tumor-promoting roles of IFI16 have been reported in cervical cancer, breast cancer, and renal cell carcinoma (RCC)." (PMID 37998338, 2023). "IFI16 and HDACs are reported to be involved in the epigenetic regulation of ERα expression in ERα− breast cancer cells." (PMID 28415616, 2017). "It has been shown that MTA1 together with IFI16 and class II HDACs was recruited and formed a complex, resulting in the epigenetic repression of ERα in ERα− breast cancer cells." (PMID 28415616, 2017). "It has been shown that MTA1 in complex with IFI16 and HDACs contributes to epigenetic repression of ERα in ERα− breast cancer cells." (PMID 28415616, 2017). "It has been reported that most breast-cancer cell lines have a decreased level of IFI16 mRNA compared with that in normal epithelial cells." (PMID 28611294, 2017). "Of these, expression of IFI16 and ANKD1 were particularly strongly associated with RAB25 and ESRP1 levels in primary breast cancer." (PMID 26646320, 2016). "IFI16-dependent STING pathway can potentiate HER2 breast cancer responses to immunotherapy." (PMID 37051596, 2023). "Furthermore, recent findings indicate the particular importance of IFI16-STING in HER2+ breast cancer: IFI16-dependent STING activation is mechanistically important in anti-HER2 responses, and the epigenetic suppression of IFI16 is linked to resistance against anti-HER2 antibodies." (PMID 38139802, 2023). "Moreover, recent study demonstrated that IFI16 was involved in the MTA1-mediated repressor complex may contribute to the epigenetic repression of ERα expression in ERα− breast cancer." (PMID 28415616, 2017). "To establish interferon induction in breast cancer MDA-MB-231 cultured cells, we looked for interferon stimulated genes (ISG) including: OAS1, OAS3, RIG1, TLR3 and IFI16 genes." (PMID 32817625, 2020). "Expression of IFI16 plays a role in resistance to tamoxifen treatment in breast cancer, and ANKD1 is involved in resistance to cisplatin resistant in ovarian and breast cancers." (PMID 26646320, 2016). "Downregulation of interferon-γ inducible protein 16 (IFI16), a direct target of EZH2, decreases stimulator of interferon genes (STING) activation and downstream CXCL10/11 expression in response to trastuzumab treatment in HER2+ breast cancer (BC)." (PMID 37198402, 2023). "IFI16 (IFN-gamma-inducible protein 16) epigenetically suppresses estrogen receptor expression, and it may affect tamoxifen sensitivity in breast cancer cells." (PMID 26646320, 2016). "In addition, MES TFs, SMAD3, SOX9, WWTR1, and IFI16 had 32, 23, 6, and 5 connections, respectively, and KEGG gene enrichment analysis revealed enrichment for ‘breast cancer’, ‘prostate cancer’, and ‘hepatocellular carcinoma’ processes in addition to ‘miRNA in cancer’ terms." (PMID 35201514, 2021). "Finally, MTA1/IFI16/HDACs corepressor complex was identified as the key epigenetic mechanism regulated by Z-LIG for the reactivation of ERα and subsequent restoration of TAM sensitivity of ERα− breast cancer cells." (PMID 28415616, 2017).
HIV-1 infection (15 papers, 2016 to 2025). The type species of lentivirus and the etiologic agent of acquired immunodeficiency syndrome (AIDS). "The first example is IFN-inducible protein 16 (IFI16), one of the best-studied cytosolic DNA sensors modulating the innate immune response to HIV-1 infection." (PMID 41373786, 2025). "This provides evidence on the role of IFI16 as a sensor for lentiviral RT products and control of the HIV-1 infection in macrophages through the induction of ISGs." (PMID 34595244, 2021). "Altogether, further studies on the role of Sp1 and its IFN-inducible inhibitors, i.e., TRIM22 and IFI16, as well as subtype-specific differences in the establishment and maintenance of latent HIV-1 infections, seem highly warranted." (PMID 32365692, 2020). "More recently, IFI16 was also found to suppress HIV-1 infection via interfering with the host transcription factor Sp1-dependent viral gene expression in an IFN signaling independent manner." (PMID 31968566, 2020). "When humans are infected with HIV-1, at least two PRRs, CGAS and IFI16, sense HIV-1 infection and induce IFN-I production." (PMID 30915053, 2019). "IFI16 is shown to be crucial for sensing the cDNA products of the abortive HIV-1 infection." (PMID 41373786, 2025). "Previous reports indicated that IFI16 restricts HIV-1 infection trough STING in macrophages but promotes HIV-1 induced CD4+ T cells death by pyroptosis and thus may drive HIV-1 pathogenesis." (PMID 36800238, 2023). "Also, primary human macrophages deprived of IFI16 (IFI16 knockdown) displayed an amplified early viral replication and accelerated virus-induced cytopathic effects after HIV-1 infection." (PMID 34595244, 2021). "Taken together, these studies suggest that IFI16 has cell-type dependent, as well as multifactorial, roles, first as a DNA sensor that activates innate immune response and second, as a direct antiviral factor that suppresses HIV-1 infection." (PMID 31968566, 2020). "Importantly, IFI16 restricts HIV-1 infection in macrophages but promotes HIV-1 induced CD4+ T cells death by pyroptosis and thus may drive HIV-1 pathogenesis." (PMID 36800238, 2023). "Thus, IFI16 might play a complex role in HIV-1 infection and latency, since it has previously been characterized as a cytosolic immune sensor of HIV-1 DNA species that boosts IFN induction in macrophages." (PMID 32365692, 2020). "To show evidences of early inflammasome sensing of HIV-1 in huNSG mice upon HIV-1 infection, we quantified mRNA expression of genes involved in inflammasome activation (NLRP3, NLRP1, NLRC4, AIM2, IFI16, ASC, CASP1, IL1Β, and IL18) in hCD45+ cells from multiple tissues collected at necropsy." (PMID 36800238, 2023). "Moreover, human immunodeficiency virus 29 DNA can be sensed by IFI16 and induce the activation of IFI16 inflammasome in the cytoplasm, which mediates the pyroptosis of CD4+ T cells during abortive HIV-1 infection." (PMID 33061806, 2020).
autoimmune disease (14 papers, 2013 to 2025). A disorder resulting from loss of function or tissue destruction of an organ or multiple organs, arising from humoral or cellular immune responses of the individual to their own tissue constituents. "On the other hand, GSK3β has been implicated in Sjögren's syndrome, an autoimmune disease associated with IFI16 overexpression and autoantibodies against IFI16 filaments." (PMID 37283074, 2023). "Recently, the IFN-induced factor IFI16 protein has been associated with B-cell dysfunction and autoimmune diseases suggesting a possible role for this protein in B-cell biology." (PMID 26185770, 2015). "We propose that the underlying scenario is the result of an ancestral and still ongoing host–pathogen arms race and that the maintenance of susceptibility alleles for autoimmune diseases at IFI16 represents an evolutionary trade-off." (PMID 24682156, 2014). "The balancing selection region in IFI16 carries a variant with opposite risk effect for distinct autoimmune diseases, suggesting antagonistic pleiotropy." (PMID 24682156, 2014). "We suggest that the underlying scenario is the result of an ancestral and still ongoing host–pathogen arms race and that the maintenance of susceptibility alleles for autoimmune diseases at IFI16 represents an evolutionary trade-off." (PMID 24682156, 2014). "Therefore, one possible explanation is that functionally different IFI16 variants were originally maintained by antagonistic pleiotropy related to immune response against pathogens, with differential susceptibility to autoimmune diseases being a consequence." (PMID 24682156, 2014). "IFI16 plays a crucial role in defence against viruses such as herpes simplex virus 1 and autoimmune diseases." (PMID 41440367, 2025). "IFI16 is involved in several autoimmune diseases, such as systemic lupus erythematous, systemic sclerosis, and Sjogren’s syndrome, Behçet disease." (PMID 41440367, 2025). "Consistently, we and others have shown that IFI16 is overexpressed in a wide range of autoimmune diseases where it triggers production of specific autoantibodies." (PMID 29892303, 2018). "We and others have previously reported the presence of anti-IFI16 antibodies in sera of patients suffering from various autoimmune diseases such as SLE, SjS, AR, SSc, and IBD." (PMID 29892303, 2018). "Recent reports have implicated IFI16 in autoimmunity, pointing to a role of PYHIN proteins in the pathogenesis of human autoimmune disease." (PMID 29892303, 2018). "Association with IFN activity indicates a possible involvement of IFI16 in some autoimmune diseases that feature high interferon levels." (PMID 26185770, 2015). "We focused on the IFI16 region, as it was detected by both the 1000 Genomes and by the HGDP genotype data, and because the region carries an autoimmune disease susceptibility variant." (PMID 24682156, 2014). "In the present study, using an in-house enzyme-linked immunosorbent assay (ELISA) we demonstrate the presence of detectable amounts of a circulating form of IFI16 in the sera from patients affected by autoimmune disorders." (PMID 23690979, 2013). "The presence of anti-IFI16 autoantibodies have been detected in many autoimmune diseases, thus the release of IFI16 in the extracellular milieu marks the first step in the development of autoimmunity." (PMID 23690979, 2013). "IFI16 may also act as a possible target in autoimmune diseases and can be found in human fibroblasts, endothelial cells, and B cells." (PMID 29743020, 2018). "IFI16 expression is deregulated in autoimmune diseases and primary cancers." (PMID 26185770, 2015). "Thus, investigations into the mechanistic cues that toggle DNA-dependent IFI16 oligomerization during contexts of PRR sensing have important implications not only for understanding antiviral immunity, but also for autoimmune diseases and immunotherapies." (PMID 37283074, 2023).
autoimmune disease (continued). "IFIT5, IFI16 and MX2, interferon-stimulated genes, both nuclear transcriptional factors, were found to be upregulated in other autoimmune diseases but not in JDM." (PMID 32110496, 2020).
cervical cancer (13 papers, 2020 to 2025). A primary or metastatic malignant neoplasm involving the cervix. "To explore the role of IFI16 in cisplatin‐induced apoptosis of cervical cancer cells, we stimulated HeLa cells with cisplatin (4 μg/mL) for 12 h after knockdown of IFI16." (PMID 40770819, 2025). "IFI16, an interferon-stimulated gene, promoted cervical cancer progression by upregulating PD-L1 expression through the activation of STING-TBK1-NF-κB pathway." (PMID 41142804, 2025). "The results suggested that inhibiting IFI16 enhanced the cisplatin sensitivity of subcutaneous implantation tumour of cervical cancer in mice." (PMID 40770819, 2025). "We constructed siRNA‐IFI16 to knock down IFI16 protein expression in human cervical cancer cell HeLa." (PMID 40770819, 2025). "It is suggested that the NF‐κB pathway is activated and the expression of IFI16 is increased with obvious nucleation during the apoptosis of human cervical cancer cells induced by cisplatin." (PMID 40770819, 2025). "To further validate this tumour‐promoting effect of IFI16 during cisplatin therapy, we established a subcutaneous implantation tumour model using mouse cervical cancer (U14) cells and conducted additional in vitro experiments." (PMID 40770819, 2025). "IFI16 plays a significant role in promoting cervical cancer progression by upregulating PD-L1 expression in the tumor microenvironment through the activation of the STING-TBK1-NF-κB signaling pathway." (PMID 39949780, 2025). "In HPV-positive cervical cancer, IFI16 levels are abnormally elevated, leading to increased PD-L1 expression in cancer cells." (PMID 39949780, 2025). "In order to explore the in vivo effect of inhibiting IFI16 combined with cisplatin, a subcutaneous implantation tumour model of mouse cervical cancer cells was constructed." (PMID 40770819, 2025). "Compared with HPV-negative cervical cancer cells, the expression levels of IFI16 and PD-L1 were higher in HPV-positive samples." (PMID 41142804, 2025). "At the same time, we found that the cisplatin sensitivity of cervical cancer cells HeLa was enhanced after knockdown of IFI16, which indicated that IFI16 played a role in resisting cisplatin‐induced apoptosis." (PMID 40770819, 2025). "The HPV E7 oncoprotein has been described to activate the TRIM21-mediated proteasomal degradation of gamma-interferon-inducible protein-16 (IFI16) in cervical cancer cell lines." (PMID 36982215, 2023). "The PRY/SPRY domain of TRIM21 interacts with γ-interferon-inducible protein-16 (IFI16) and mediates the degradation of IFI16 in a K33-linked manner, leading to the inhibition of cell pyroptosis and self-escape from immune surveillance, which may account for the occurrence of cervical cancer." (PMID 36159815, 2022). "Moreover, IFI16 promoted the expression of PD-L1 and facilitated the oncogenic behaviors of cervical cancer cells." (PMID 41142804, 2025). "The role of IFI16 in cervical cancer progression deserves further study." (PMID 40770819, 2025). "We examined the role and mechanism of IFI16 in cisplatin treatment of cervical cancer." (PMID 40770819, 2025). "Targeted inhibition of IFI16 may be a new way to increase cisplatin sensitivity of cervical cancer cells." (PMID 40770819, 2025). "Last, IFI16 promotes cervical cancer progression through the NF-kB pathway." (PMID 37693315, 2023).
cervical cancer (continued). "By promoting tumor progression and contributing to an immunosuppressive microenvironment, IFI16 presents a potential therapeutic target to restore immune surveillance and improve treatment outcomes in HPV-positive cervical cancer." (PMID 39949780, 2025). "IFI16 and PYCAED serve as oncogenes in cervical cancer and gastric cancer, respectively." (PMID 34568046, 2021). "We observed that cisplatin activated STING signalling in cervical cancer cells is related to cisplatin‐induced proinflammatory factor expression, but may not be related to IFI16/NF‐κB resistance to cisplatin‐induced apoptosis." (PMID 40770819, 2025).
Sjögren’s syndrome (11 papers, 2013 to 2025). "SLE, Sjӧgren’s syndrome, systemic sclerosis and rheumatoid arthritis have all been linked to anti-IFI16 antibodies." (PMID 37393341, 2023). "Increased extracellular IFI16 and the presence of anti-IFI16 autoantibodies have been reported in several rheumatological disorders including, Sjögren’s syndrome." (PMID 40526428, 2025). "It has also been suggested that IFI16 filamentation with DNA contributes to its autoantigen status in Sjögren's syndrome." (PMID 37283074, 2023). "Further, it has been suggested that oligomerization of IFI16 upon dsDNA stimulates the establishment of IFI16 as an autoantigen in target tissues of Sjögren’s syndrome." (PMID 35575489, 2022). "Thus, NLRP3, AIM2 and IFI16 are components of the innate immune system that are activated in Sjögren syndrome." (PMID 41440367, 2025). "Interestingly, this process may also have a role in self-tolerance, as IFI16 forms oligomers spontaneously in Sjogren’s syndrome." (PMID 35189960, 2022). "IFI16 was detected in serum from patients with SLE, Sjӧgren’s syndrome, systemic sclerosis, rheumatoid arthritis and psoriasis." (PMID 37393341, 2023).
hepatocellular carcinoma (10 papers, 2019 to 2025). A malignant tumor that arises from hepatocytes. "Experiments in hepatocellular carcinoma tissues from patients have shown that IFI16 induces the formation of inflammasomes in tumor cells, promoting cell death, an effect that can be inhibited by a caspase-1 inhibitor." (PMID 38523155, 2024). "One report showed that Ifi16 suppresses cell viability and increases apoptosis in hepatocellular carcinoma (HCC) cell lines." (PMID 38139000, 2023). "The suppressive role of IFI16 against malignant phenotypes in tumor cells has been reported in hepatocellular carcinoma (HCC), prostate cancer, and thyroid cancer." (PMID 37998338, 2023). "For confirming the presence of IFI16, ZBP1/DAI, and AIM2 in hepatocytes rather than in immune cells possibly contaminating the PWH cultures, woodchuck WCH-17 hepatoma cells were treated with HSV-60 and poly(dA:dT)." (PMID 34671360, 2021).
prostate carcinoma (9 papers, 2010 to 2024). A carcinoma that arises from epithelial cells of the prostate gland. "The authors suggested that the loss of IFI16 expression contributed to the development of breast or prostate cancer." (PMID 28611294, 2017). "Re-expression of IFI16 in prostate cancer cells of a mouse model relieved tumor growth and simultaneously induced anti-tumor immune activation." (PMID 38523155, 2024). "Further, we noted earlier that activation of the AR in human prostate cancer cell line PC-3 stimulated the expression of IFI16 PYHIN proteins." (PMID 33923931, 2021). "Increased expression of the IFI16 proteins in human normal PrECs, PC-3 prostate cancer cell line, and human normal diploid fibroblasts (HDFs) associated with the onset of cellular senescence." (PMID 33923931, 2021). "Ectopic expression of IFI16 in prostate cancer cell lines increases p21 expression and inhibits E2F-stimulated transcription." (PMID 26809031, 2016). "Similarly, the IFI16 protein can also bind to pRb protein and increased levels of IFI16 protein in prostate cancer cells inhibit the E2F1-mediated transcription." (PMID 20052289, 2010). "Furthermore, overexpression of IFI16 protein in PC-3 human prostate cancer cell line resulted in senescence-like phenotype and reduced telomere length." (PMID 20052289, 2010).